HYI (hydroxypyruvate isomerase (putative))
Description:
May catalyzes the reversible isomerization between hydroxypyruvate and 2-hydroxy-3-oxopropanoate (also termed tartronate semialdehyde).
Synonyms: HT036
Tractability: Antibody: the Human Protein Atlas places it where antibodies can reach. PROTAC: ubiquitination databases record sites on it.
Gene: Protein-coding gene on chromosome 1 (43,450,607 to 43,453,999, reverse strand). Ensembl gene ENSG00000178922.
Subcellular location (Human Protein Atlas): Cytosol; Plasma membrane; Golgi apparatus
Gene Ontology:
Molecular function: protein binding; hydroxypyruvate isomerase activity
Biological process: glyoxylate metabolic process
Genetic constraint (gnomAD): Loss-of-function variants: 50 observed, 39.61 expected, observed/expected ratio (o/e) 1.26, 90% interval 1 to 1.6. The synonymous counts are far from expectation, so gnomAD's model fits this gene poorly and the ratio says little. Missense variants: 465 observed, 333.79 expected, observed/expected ratio (o/e) 1.39, 90% interval 1.29 to 1.5. Synonymous variants: 186 observed, 139.5 expected, observed/expected ratio (o/e) 1.33, 90% interval 1.18 to 1.51.
Homologues: Orthologues: chimpanzee HYI (97% identical), macaque HYI (96% identical), rat Hyi (88% identical), guinea pig HYI (83% identical), pig HYI (83% identical), rabbit HYI (79% identical), dog HYI (71% identical), zebrafish hyi (61% identical), tropical clawed frog hyi (58% identical), Drosophila melanogaster Gip (35% identical), Caenorhabditis elegans C05D11.5 (35% identical).
Diseases named in the same sentence as HYI in open-access papers:
HYI is named in the same sentence as 5 diseases in open-access papers, as found by Europe PMC text mining. Sharing a sentence is not in itself a finding about the gene and the disease. The quoted sentences say what the papers report.
melanoma (1 paper, 2022). A malignant, usually aggressive tumor composed of atypical, neoplastic melanocytes. "This identified somatic eQTLs frequently mutated in melanoma, including 12 that were almost exclusively mutated in melanoma, and two loci that regulate the expression of DAAM1 (191 bp downstream) and HYI (95 kb away)." (PMID 36171609, 2022).
diseases of the central nervous system (1 paper, 2025). "These include genes involved in neurodegeneration (EIF5), diseases of the central nervous system (IPO13, ST3GAL3), tobacco addiction (CHRNB4, PSMA4), fatty acid metabolism (ACSBG1), and skin conditions (HYI, ELOVL1)." (PMID 40074595, 2025).
psychiatric disorder (1 paper, 2022). A disorder characterized by behavioral and/or psychological abnormalities, often accompanied by physical symptoms. "It is the first time HYI and eIF4H were found to associate with psychiatric disorders." (PMID 35509884, 2022).
HYI also shares sentences with these, for which no sentence is quoted: lung adenocarcinoma (1 paper); renal clear cell carcinoma (1).